OR3A3 (olfactory receptor family 3 subfamily A member 3)
Description:
Odorant receptor.
Synonyms: OR17-201; OR3A6; OR3A7; OR3A8P; OR17-137; OR17-16
Gene: Protein-coding gene on chromosome 17 (3,411,370 to 3,424,070, forward strand). Ensembl gene ENSG00000159961.
Subcellular location: Cell membrane
Pathways (Reactome):
Sensory Perception: Expression and translocation of olfactory receptors
Genetic constraint (gnomAD): Loss-of-function variants: 3 observed, 3.51 expected, observed/expected ratio (o/e) 0.85, 90% interval 0.38 to 1.79. That is too few expected variants to judge how well the gene tolerates losing a copy. Missense variants: 225 observed, 284.33 expected, observed/expected ratio (o/e) 0.79, 90% interval 0.71 to 0.88. Synonymous variants: 88 observed, 115.13 expected, observed/expected ratio (o/e) 0.76, 90% interval 0.64 to 0.91.
Homologues: Paralogues in human: OR3A2 (90% identical), OR3A1 (77% identical), OR1K1 (47% identical), OR7D4 (46% identical), OR1J1 (45% identical), OR1F1 (44% identical), OR7A17 (44% identical), OR10R2 (44% identical), OR1A2 (44% identical), OR1J4 (44% identical), OR7C1 (44% identical), OR7D2 (44% identical), and 116 more.
Diseases named in the same sentence as OR3A3 in open-access papers:
OR3A3 is named in the same sentence as 1 disease in open-access papers, as found by Europe PMC text mining. Sharing a sentence is not in itself a finding about the gene and the disease. The quoted sentences say what the papers report.
Anosmia (1 paper, 2025). An inability to perceive odors. "Variants in OR3A3 may affect olfactory sensitivity and perception, potentially impacting conditions related to smell, such as anosmia or other sensory processing disorders." (PMID 40295545, 2025).